STAT3 (signal transducer and activator of transcription 3)
Diseases named in the same sentence as STAT3 in open-access papers (continued):
Sharing a sentence is not in itself a finding about the gene and the disease.
psoriasis (continued). "Furthermore, psoriasis-related factors, such as IL-17A, IL-17F, IL-22, and IL-23R, can be transcriptionally activated by STAT3, suggesting that STAT3 plays a promoting role in psoriasis development." (PMID 36835162, 2023). "Furthermore, LINC02541 was consistently downregulated in psoriasis (P = 2.6 × 10–20, FC = 0.54), AD (P = 4.0 × 10–10, FC = 0.54), and Netherton syndrome (P = 1.0 × 10–3, FC = 0.55), while STAT3 was upregulated in all 3 diseases." (PMID 38131377, 2023). "In addition to the MAPK/AP-1 and NF-κB signalling pathways, STAT3 also plays an important role in psoriasis." (PMID 37445960, 2023). "Psoriasis is associated with the overexpression of JAK1 and STAT3." (PMID 37629529, 2023). "Overexpression of the active form of STAT3 in psoriasis leads to increased numbers of IL-17–producing cells and mediates the production of IL-23, resulting in the amplification of the Th17 pathway, while STAT1 stimulates the upregulation of keratin 17 expression." (PMID 37597582, 2023). "Moreover, the expression of p-STAT1 and p-STAT3 was elevated in the dermis of PS+T, analogous with the results of the T cell secretory profile and contributing to the activation loop of psoriasis." (PMID 37597582, 2023). "Several studies have shown the involvement of STAT3 activation in psoriasis." (PMID 37226685, 2023). "STAT3 distinctly contributes to the inflammatory response in psoriasis." (PMID 37298949, 2023). "STAT3, a transcription factor, has been shown to control cell cycling and proliferation in keratinocytes, making it a critical signaling pathway involved in the pathological development of psoriasis." (PMID 35351863, 2022). "In conclusion, previous studies have reported that oral astilbin could inhibit Th17 cell differentiation and ameliorate IMQ‐induced psoriasis‐like skin lesions by inhibiting the Jak3/Stat3 signalling pathway in BALB/c mice." (PMID 35023281, 2022). "STAT3 conveys signals from psoriatic cytokines, such as IL-6, IL-17, IL-21, IL-22, and IL-23, to the nucleus and triggers an inflammatory response, which is involved in the pathogenesis of psoriasis." (PMID 35116069, 2022). "For example, miR-320b is down-regulated in the tissues of psoriasis and could participate in the pathogenesis of psoriasis via regulating the STAT3 and SAPK/JNK signaling pathways." (PMID 36618400, 2022). "Notably, a clinical study reported that a STAT3 inhibitor improved the skin lesions of patients with psoriasis and indicated that STAT3 can serve as a drug target for psoriasis." (PMID 35116069, 2022). "Suppression of PI3K/AKT/mTOR (mammalian target of rapamycin) signaling has also been suggested in the treatment of psoriasis and the antioxidant protein, HO-1, may mitigate IMQ-induced psoriasis-like inflammation by blocking the STAT3 signal." (PMID 35720176, 2022). "We speculated that the effect of etanercept on psoriasis may be achieved through inhibition JAK/STAT3 signaling pathway." (PMID 36444619, 2022). "A study showed that miR-203 could inhibit the expression of SOCS3 by directly binding to the 3’-UTR of SOCS3 and promoted the degradation of SOCS3 mRNA, thereby activating the JAK2/STAT3 signaling pathway to promote the progression of psoriasis." (PMID 36618400, 2022). "STAT3 signalling and IL-6 are closely related to the pathogenesis of psoriasis, and we hypothesized that KLHDC7B-DT might participate in regulating the inflammatory response and be involved in the pathogenesis of psoriasis." (PMID 35586566, 2022). "In conclusion, our findings indicated that etanercept could inhibit the JAK/STAT3 pathway to reduce Th17/Treg ratio and promote M2 polarization, thereby alleviating psoriasis of mice." (PMID 36444619, 2022). "In addition, compound 1 also effectively reduced the chemokines and STAT3 phosphorylation in psoriasis HaCaT cells." (PMID 36015080, 2022).
psoriasis (continued). "Accumulating evidence suggests that the ERK and STAT3 pathways play a crucial role in the pathogenesis of psoriasis by inducing keratinocyte proliferation and inflammation, and the levels of ERK and STAT3 in psoriatic lesions are also higher than those in normal skin." (PMID 36555642, 2022). "Similar studies also confirmed that activated HO-1 could significantly mitigate IMQ-induced psoriasis-like inflammation by blocking STAT3 signaling pathway." (PMID 36178125, 2022). "STAT3 signaling regulates epidermal keratinocyte and immune cell responses, and hyperactivation of STAT3 signaling plays a critical role in the pathogenesis of T cell related diseases such as psoriasis." (PMID 36741386, 2022). "ANGPTL4 could promote keratinocyte proliferation and inflammatory response via ERK1/2 and STAT3 dependent signaling pathways in psoriasis." (PMID 35860030, 2022). "Besides, the activation of JAK/STAT, STAT3 in particular, is deeply involved in psoriasis, accelerating psoriatic KCs proliferation, angiogenesis, and T cells abnormal differentiation." (PMID 36178125, 2022). "Mechanically, epidermal IL-17E expression is upregulated by IL-17A in psoriasis, and through its receptor IL-17RB on keratinocytes, it promotes keratinocyte proliferation and production of inflammatory cytokines and chemokines via STAT3 activation." (PMID 35075118, 2022). "Activation of PI3K and STAT3 promotes the excessive proliferation and abnormal differentiation of KC, infiltration of inflammatory cells, and secretion of cytokines (IL-6, IL-17, IL-22, and IL-23) in psoriasis." (PMID 35720176, 2022). "Hyperproliferation of keratinocytes in psoriasis correlates with the STAT3 pathway." (PMID 34054833, 2021). "Furthermore, targeting STAT3 has been suggested as a potential therapeutic approach in diseases like MS, psoriasis and RA." (PMID 34054852, 2021). "Moreover, IL-22 has a pathogenic role in psoriasis, and IFN-γ can enhance the basic expression of a-STAT3, thereby weakening the response of keratinocytes to IL-22." (PMID 34044769, 2021). "This inhibition led to the suppression of STAT3 and NF-κB phosphorylation, which play important roles in the pathogenesis of psoriasis, and blocked STAT3 and NF-κB signaling, thereby reducing the proliferation of psoriasis-induced HaCaT cells." (PMID 34209224, 2021). "In psoriasis mice induced by imiquimod, curcumin could improve the pathological injuries of the mouse skin, reduced the expressions of IL-6, p-STAT3, and its downstream proteins." (PMID 34337082, 2021). "It is also well known that STAT3 is activated in skin lesions of psoriasis, a chronic skin disease." (PMID 34679602, 2021). "Numerous studies have demonstrated that inflammation related pathways, such as nuclear factor-kappa B (NF-κB) pathways, signal transducer and activator of transcription 3 (STAT3) pathways and mitogen-activated protein kinase (MAPKs) pathways were involved in psoriasis." (PMID 34925011, 2021). "In turn, activation of Nrf2/HO-1 by TGN also inhibits activation of NF-κB and STAT3 which are the key transcription factors in psoriasis pathogenesis and promote the skin defense system while reducing the expression of immune mediators and epidermal proliferation." (PMID 35186957, 2021). "The most effective plant extracts, Humulus lupulus (HL), Hypericum perforatum (HP) and Curcuma amada (CA), were then tested for their effect on the JAK/STAT3 pathway and the marker of hyperproliferation in psoriasis, KRT17, that is regulated by the transcription factor NF-κB." (PMID 33801280, 2021). "Furthermore, overexpression was detected for the JAK2, STAT1 and STAT3 genes, which is in agreement with previous reports utilizing similar combinatorial stimulation used for modeling psoriasis in keratinocytes." (PMID 33986690, 2021). "In fact, STAT3 hyperactivation has been found in numerous cell types involved in psoriasis." (PMID 34925011, 2021).
psoriasis (continued). "Lyn has been validated for specific increases in protein levels in human psoriatic lesions and is involved in regulating the expression of STAT3 and the NF-κB pathway to mediate a chronic inflammatory syndrome resembling human psoriasis in a mouse model by pan-genomic profiling." (PMID 33995034, 2021). "In addition, IL-22 induces STAT3 phosphorylation; this is related to the induction of acanthosis (keratinocyte proliferation) and dermal inflammation in psoriasis." (PMID 34943117, 2021). "Experimental data we obtained support our model and the hypothesis that in psoriasis low level of PPARγ activity stimulates IL17 synthesis because STAT3 and RORC became less suppressed." (PMID 34445309, 2021). "Specifically, two STAT molecules, STAT1 and STAT3, are crucial in the pathogenesis of psoriasis." (PMID 34884596, 2021). "Therefore, PKM2 inhibition and consequent STAT3 suppression seem to offer another therapeutic modality for psoriasis." (PMID 33990689, 2021). "MAPK/STAT3 activation plays an important role in the pathogenesis of psoriasis." (PMID 34025642, 2021). "Nevertheless, research regarding STAT3 as treatment for psoriasis has been few." (PMID 34445513, 2021). "Therefore, other researchers have instead applied topical applications of STAT3 inhibitors, and the results indicated an improvement in approximately 75% of patients with psoriasis." (PMID 34445513, 2021). "However, STAT3 inhibitors have the possibility of being an effective treatment option and alternative for psoriasis." (PMID 34445513, 2021). "Furthermore, increased expression of active STAT3 is often detectable in the epidermis of psoriatic lesions, and pharmacological intervention to inhibit STAT3 improved psoriasis-like skin lesions in mice." (PMID 34831283, 2021). "STAT3 together with NF-κB regulates the expression of genes that control cell survival and proliferation, and inhibition of these transcription factors is a promising therapeutic strategy in psoriasis." (PMID 34834106, 2021). "Together, our data show that curcumol reduces proliferation and inflammatory gene expression in stimulated keratinocytes by inhibiting the JAK1/STAT3 signaling, suggesting that it might serve as a potential therapeutic option for the treatment of psoriasis." (PMID 34314383, 2021). "Although this study presents limitations in its sample size and inconsistency in the histology and differentiation of the cancers, results suggest that psoriasis patients do not have a predisposition to STAT3 activation." (PMID 34679602, 2021). "STAT3 is another key transcription factor involved in psoriasis." (PMID 34925011, 2021). "Additionally, we analyzed the effect of the plant extracts on inflammation and proliferation-related pathways in psoriasis, such as STAT3 and NF-κB." (PMID 33801280, 2021). "STAT3 activation is observed both in psoriasis and cancers, however, STAT3 activation in keratinocytes involved in the pathogenesis of psoriasis; i.e., inflammatory STAT3 activation, may differ from oncogenic stimulation of STAT3 in cancers." (PMID 34679602, 2021). "In addition, the combination of psoriasis cytokines induced the nuclear translocation of the p65 subunit of NFκB and the phosphorylation of STAT3, as shown in immunocytochemical stainings." (PMID 33801280, 2021). "Furthermore, ERBB4 overexpression increased the expression of psoriasis-related genes and inflammatory genes, and the levels of phospho-STAT3 (Tyr705), phospho-STAT3 (Ser727), and phospho-NF-κB p65 (Ser311) in the presence or absence of M5 treatment." (PMID 34667159, 2021). "In this study, to ascertain whether patients with psoriasis have a predisposition to STAT3 activation, we examined phosphorylated STAT3 in cancer cells of psoriasis patients via immunohistochemistry." (PMID 34679602, 2021). "In addition, topical treatment in imiquimod-induced psoriasis-like lesions on the mice model with luteolin-7-glucoside reduced the presence of STAT3 in the nucleus of skin cells." (PMID 34943117, 2021).
psoriasis (continued). "However, in psoriasis, it also triggers early activation of STAT3, NF-κB, and MAPKs in keratinocytes." (PMID 34831283, 2021). "Here, we first review new insights regarding the pathogenesis of psoriasis, as it relates to DCs, Langerhans cells, macrophages, the signal transducer and activator of transcription 3 pathway, and aryl hydrocarbon receptor in cutaneous vascular endothelial cells." (PMID 33050592, 2020). "In addition, transgenic mice, in which keratinocytes express a constitutively active form of STAT3, develop psoriasis-like skin lesions spontaneously." (PMID 32908937, 2020). "The key role of STAT3 in the development of psoriatic lesion is further supported by a study showing that treatment with ustekinumab (a monoclonal antibody that targets IL-12 and IL-23 and is used clinically for psoriasis) down-regulates the expression of STAT3 in psoriatic patients." (PMID 31710084, 2019). "Besides, SIRT1 has been shown to reduce the severity of lesions in the Aldara-induced psoriasis model via negatively regulating STAT3 activation." (PMID 31495284, 2019). "Therefore, the targeting STAT3 pathway has been a promising target for the development of psoriasis therapies." (PMID 30894513, 2019). "CDC6 expression is upregulated in epidermal cells in psoriatic lesions and it could be induced by IL-22/STAT3 signaling, a key signaling pathway involved in the pathogenesis of psoriasis, in keratinocytes." (PMID 30894513, 2019). "STAT3 is an essential player to be responsible for the antibacterial/fungal type 3 (Th17) immune response and is considered to function as a central player in psoriasis pathogenesis." (PMID 30894513, 2019). "This leads to the hypothesis that STAT3 and STAT5, which regulate Th17, are possibly associated with psoriasis." (PMID 31569642, 2019). "Therefore, decreased total protein levels of STAT3 is indicative of an anti-psoriasis effect of MEDD." (PMID 31791315, 2019). "Indeed, it was reported that STAT3 inhibitor not only inhibited the development of psoriasiform lesions in K5.Stat3C mice but also improved psoriatic lesions in psoriasis patients." (PMID 30894513, 2019). "Moreover, gene polymorphisms of IL23A, IL23R, STAT3, RUNX3, and TYK2 have also been identified as susceptibility factors for developing psoriasis." (PMID 31649667, 2019). "Moreover, BBR inhibits IMQ-induced psoriasis-like skin lesion in mice and significantly downregulates the phosphorylation level of STAT3 in keratinocytes and IMQ-induced murine epidermis." (PMID 30894513, 2019). "Specific efforts have focused on downstream anti-inflammatory effectors of GC-signaling such as GC-Induced-Leucine-Zipper (GILZ), which suppresses Th17 responses and antagonizes multiple pro-inflammatory signaling pathways involved in psoriasis, including AP-1, NF-κB, STAT3, and ROR-γt." (PMID 31572404, 2019). "Indeed GILZ is ideal as it interferes with multiple levels of pro-inflammatory signaling, including pathways involved in psoriasis like AP-1, NF-κB, STAT3, and ROR-γt." (PMID 31572404, 2019). "Indeed, a recent study has shown that calcipotriol, which has been used widely for the treatment of psoriasis, inhibits proliferation of keratinocytes by downregulating phosphorylation of STAT3." (PMID 30279326, 2018). "Finally, several GWA studies detected correlations between psoriasis and alternative forms of the STAT3 locus." (PMID 29316631, 2018). "Moreover, IL-6, IL-21, IL-22, IL-26, and IL-29, which participate to the amplification and maintenance of the inflammatory loop in psoriasis, all signal via STAT3." (PMID 29316631, 2018). "Notably, many of the cytokines produced by activated Th17 cellsinduce keratinocyte proliferation in psoriasis patients, and following receptorbinding and downstream signaling via STAT3, IL-23 contributes to the development ofpsoriasis." (PMID 29630472, 2018). "Therefore, VEGF and STAT3 protein expression levels are higher in the skin lesions of psoriasis patients than in normal skin." (PMID 29292715, 2017).
psoriasis (continued). "STAT3 inhibitors markedly improved psoriasis symptoms in patients." (PMID 27941650, 2016). "Interestingly, mice with constitutively active STAT3 in keratinocytes, develop a psoriasis like phenotype." (PMID 26999594, 2016). "However, in psoriasis, Stat3 was consistently activated in epidermal keratinocytes, which was assumed to recapitulate persistent wound healing reaction." (PMID 26893174, 2016). "The abnormal activation of Stat3, a known transcription factor that induces inflammation and regulates cell differentiation, is directly involved in the pathogenesis and development of psoriasis." (PMID 26893174, 2016). "It has been proven that STAT3 plays a role in keratinocyte differentiation and proliferation, is activated in psoriatic lesions and is a therapeutic target for the treatment of psoriasis." (PMID 27711196, 2016). "The in vivo protective effect of HO-1 induction on psoriasis was likely ascribed to the inhibition of Stat3 activation in keratinocytes, but other pathological mechanisms may exist." (PMID 26893174, 2016). "Unexpectedly, in GILZ-Tg mice, the severity of IMQ-induced psoriasis-like skin lesions as well as induction of cytokines commonly up-regulated in human psoriasis (Il-17, Il-22, Il-23, Il-6, S100a8/a9, and Stat3) was significantly more pronounced relative to GILZ-Wt mice." (PMID 27934944, 2016). "In vitro, JAK3/STAT3 signaling acts as a target in the treatment of psoriasis models." (PMID 27711196, 2016). "Stat3 is essential for Th17 differentiation and the inhibition of Treg cell functions; however, increased Th17 cell infiltration and reduced Treg function have also been reported in psoriasis patients." (PMID 26893174, 2016). "STAT3 has been shown to be required for the development of psoriasis in keratinocytes." (PMID 25013907, 2014). "Although mice with epidermal acanthosis and dermal inflammation induced by IL-23 injection into the ear are not an exact model for psoriasis, many of the features in this model, such as IL-22 upregulation and STAT3 activation, are similar to the features evident in psoriasis." (PMID 23956763, 2013). "Thus, PPAR β/δ transgenic mice exhibit psoriasis-typical immunological changes, STAT3 activation, as well as psoriasis – specific gene dysregulation." (PMID 22606335, 2012). "Since PPAR β/δ may act as a direct antagonist to PPARγ and PPARγ activation inhibits STAT3, activation of PPARγ unsurprisingly has a mild inhibitory effect on psoriasis." (PMID 22606335, 2012). "STAT3 and ERK1/2 are known to be closely associated with psoriasis." (PMID 22808266, 2012). "Thus, at least two kinase pathways converge on STAT3 phosphorylation both in psoriasis and PPARβ/δ mice." (PMID 20300524, 2010). "Mechanistic analyses in our study revealed elevated expression of phosphorylated STAT1 and STAT3 in T2DM patients, where these phosphoproteins were also implicated in the pathogenesis of autoimmune diseases such as rheumatoid arthritis, systemic lupus erythematosus, and psoriasis." (PMID 41030441, 2025). "Additionally, OCFAs may interact with the STAT3 pathway, which plays a critical role in psoriasis pathogenesis." (PMID 40356914, 2025). "Moreover, as a critical intracellular kinase within this pathway, tyrosine kinase 2 mediates IL-23 receptor signaling and downstream STAT3 activation, making it a promising therapeutic target for disrupting the IL-23/IL-17-driven inflammatory cascade in psoriasis." (PMID 40507893, 2025). "Notably, FFE reduced the phosphorylation of STAT3 in the psoriasis-like mouse model." (PMID 37629529, 2023). "In addition, IL-9 is also increased in psoriasis patients, which not only promotes Th17-associated inflammation and angiogenesis in psoriasis, but also facilitates P-selectin expression and platelet activation via JAK2/STAT3 pathway in deep venous thrombosis." (PMID 37654493, 2023). "Thus, the IL‐6/AKT/STAT3/LMO4 pathway is a potential therapeutic target for psoriasis treatment." (PMID 38156380, 2023).